H2BC4 (H2B clustered histone 4)
Description:
Core component of nucleosome. Nucleosomes wrap and compact DNA into chromatin, limiting DNA accessibility to the cellular machineries which require DNA as a template. Histones thereby play a central role in transcription regulation, DNA repair, DNA replication and chromosomal stability. DNA accessibility is regulated via a complex set of post-translational modifications of histones, also called histone code, and nucleosome remodeling. Has broad antibacterial activity. May contribute to the formation of the functional antimicrobial barrier of the colonic epithelium, and to the bactericidal activity of amniotic fluid.
Synonyms: H2B/l; H2BFL; HIST1H2BC; H2B.1; H2BC10; H2BC6; H2BC7; H2BC8; dJ221C16.3
Tractability: Small molecule: a structure with a bound ligand is known. PROTAC: UniProt records ubiquitination sites on it; ubiquitination databases record sites on it.
Gene: Protein-coding gene on chromosome 6 (26,086,317 to 26,124,016, reverse strand). Ensembl gene ENSG00000180596.
Subcellular location: Nucleus; Chromosome
Subcellular location (Human Protein Atlas): Nucleoplasm; Cytosol
Pathways (Reactome):
Gene expression (Transcription): B-WICH complex positively regulates rRNA expression; DNA methylation; ERCC6 (CSB) and EHMT2 (G9a) positively regulate rRNA expression; MLL4 and MLL3 complexes regulate expression of PPARG target genes in adipogenesis and hepatic steatosis; NoRC negatively regulates rRNA expression; PRC2 methylates histones and DNA; RNA Polymerase I Promoter Escape; RNA Polymerase I Promoter Opening; RUNX1 regulates genes involved in megakaryocyte differentiation and platelet function; RUNX1 regulates transcription of genes involved in differentiation of HSCs; Regulation of endogenous retroelements by KRAB-ZFP proteins; Regulation of endogenous retroelements by Piwi-interacting RNAs (piRNAs); Regulation of endogenous retroelements by the Human Silencing Hub (HUSH) complex; SIRT1 negatively regulates rRNA expression; Transcriptional regulation by small RNAs
Chromatin organization: CHD1 and CHD2 subfamily; CHD6, CHD7, CHD8, CHD9 subfamily; ChAHP complex assembly; HATs acetylate histones; HDACs deacetylate histones; Interaction of NuRD complexes with transcription factors; NuRD complex assembly
DNA Repair: Cleavage of the damaged purine; Cleavage of the damaged pyrimidine; Nonhomologous End-Joining (NHEJ); Processing of DNA double-strand break ends; Recognition and association of DNA glycosylase with site containing an affected purine; Recognition and association of DNA glycosylase with site containing an affected pyrimidine; Recruitment and ATM-mediated phosphorylation of repair and signaling proteins at DNA double strand breaks
Cell Cycle: Condensation of Prophase Chromosomes; Deposition of new CENPA-containing nucleosomes at the centromere; G2/M DNA damage checkpoint; Inhibition of DNA recombination at telomere; Packaging Of Telomere Ends
Developmental Biology: Activation of anterior HOX genes in hindbrain development during early embryogenesis; Chromatin modifications during the maternal to zygotic transition (MZT); Replacement of protamines by nucleosomes in the male pronucleus; Transcriptional regulation of granulopoiesis
Disease: Defective pyroptosis; Dengue Virus-Host Interactions
and 18 more pathways
Gene Ontology:
Molecular function: identical protein binding; protein binding; DNA binding; structural constituent of chromatin; protein heterodimerization activity
Biological process: antibacterial humoral response; antimicrobial humoral immune response mediated by antimicrobial peptide; defense response to Gram-positive bacterium; innate immune response in mucosa; chromatin organization; nucleosome assembly
Cellular component: extracellular exosome; extracellular region; nucleus; nucleoplasm; nucleosome; chromosome
Genetic constraint (gnomAD): Loss-of-function variants: 10 observed, 6.42 expected, observed/expected ratio (o/e) 1.56, 90% interval 0.91 to 1.94. That is too few expected variants to judge how well the gene tolerates losing a copy. Missense variants: 176 observed, 178.05 expected, observed/expected ratio (o/e) 0.99, 90% interval 0.87 to 1.12. Synonymous variants: 146 observed, 75.15 expected, observed/expected ratio (o/e) 1.94, 90% interval 1.66 to 1.99.
Homologues: Orthologues: guinea pig H2BC4 (100% identical), macaque H2BC7 (100% identical), mouse H2bc8 (100% identical), rat Hist1h2bg (100% identical). Paralogues in human: H2BC10 (100% identical), H2BC6 (100% identical), H2BC7 (100% identical), H2BC8 (100% identical), H2BC12 (99% identical), H2BC15 (99% identical), H2BC21 (99% identical), H2BC5 (99% identical), H2BC9 (99% identical), H2BC11 (98% identical), H2BC13 (98% identical), H2BC17 (98% identical), and 9 more.
Diseases named in the same sentence as H2BC4 in open-access papers:
H2BC4 is named in the same sentence as 7 diseases in open-access papers, as found by Europe PMC text mining. Sharing a sentence is not in itself a finding about the gene and the disease. The quoted sentences say what the papers report.
breast carcinoma (2 papers, 2021 to 2023). "H2BC4 and H4C1 are also overexpressed in breast cancer and the first is overexpressed in its metastatic relapse." (PMID 33662042, 2021).
COVID-19 (1 paper, 2025). A disease caused by infection with severe acute respiratory syndrome coronavirus 2. "JAK3, ICAM1, and H2BC4 were identified as markers of higher COVID-19 severity." (PMID 41155463, 2025). "The COVID-19 high-stage-specific markers (i.e., FOS, CXCL8, HLAA, JAK3, ICAM1, and H2BC4) were overexpressed in higher-stage samples, that is, increased expression levels of the markers were observed in asymptomatic to critical samples." (PMID 41155463, 2025). "Based on our results, we suggest that controlling high-severity-specific markers (FOS, CXCL8, HLA-A, JAK3, ICAM1, and H2BC4) and low-severity-specific markers (IL1B, CD3D, CD4, CCL5, and SNRPB) may prevent COVID-19 progression." (PMID 41155463, 2025).
pancreatic cancer (1 paper, 2025). "H2BC4 is a prognostic biomarker in pancreatic cancer and is associated with gemcitabine resistance in LUAD." (PMID 41375045, 2025).
H2BC4 also shares sentences with these, for which no sentence is quoted: systemic lupus erythematosus (2 papers); Alcoholism (1); glioblastoma (1); tumor (1).